SDHAP1 (SDHA pseudogene 1)
Synonyms: formerly SDHAL1; SDHALP1
Gene: Transcribed unprocessed pseudogene on chromosome 3 (195,963,335 to 195,990,258, reverse strand). Ensembl gene ENSG00000185485.
Diseases named in the same sentence as SDHAP1 in open-access papers:
SDHAP1 is named in the same sentence as 7 diseases in open-access papers, as found by Europe PMC text mining. Sharing a sentence is not in itself a finding about the gene and the disease. The quoted sentences say what the papers report.
ovarian carcinoma (8 papers, 2020 to 2026). A malignant neoplasm originating from the surface ovarian epithelium. "The functional analysis indicated that the SDHAP1/miR-4465/EIF4G2 regulatory axis was linked to the apoptosis induced by paclitaxel in ovarian cancer." (PMID 41362671, 2026). "Succinate dehydrogenase complex flavoprotein subunit A pseudogenene 1(SDHAP1) is located on chromosome 3, encoding lncRNA SDHAP1 which is associated with chemoresistance in ovarian cancer." (PMID 34796116, 2021). "Recently, there have been reports of the abnormal increased expression of the lncRNA succinate dehydrogenase complex flavoprotein subunit A pseudogene 1 (SDHAP1) in ovarian cancer cell lines that are resistant to the chemotherapy drug paclitaxel." (PMID 41362671, 2026). "Prior research has indicated a connection between the lncRNA SDHAP1 and resistance to chemotherapy drugs in ovarian cancer, even though research specifically examining this relationship remains scarce." (PMID 41362671, 2026). "Investigations have shown that SDHAP1 is overexpressed in ovarian cancer cell lines that are resistant to paclitaxel, such as Hey-8 and SKOV3, and this increased SDHAP1 expression is associated with decreased levels of miR-4465." (PMID 41362671, 2026). "Silencing of SDHAP1 induced re-acquirement of chemo-sensitivity to PTX in ovarian cancer cells in vitro." (PMID 34796116, 2021). "Recently, it was found that lncRNA SDHAP1 upregulated the expression of EIF4G2 by reducing miR-4465 levels in ovarian cancer cells." (PMID 33153035, 2020). "Moreover, inhibiting the expression of SDHAP1 was found to restore sensitivity to paclitaxel chemotherapy in ovarian cancer cells in laboratory studies." (PMID 41362671, 2026). "Nevertheless, research on the regulatory role of SDHAP1 in chemotherapeutic resistance in ovarian cancer is scarce, and the precise mechanisms are still unknown." (PMID 41362671, 2026). "A recent study showed that lncRNA SDHAP1 upregulated the expression of EIF4G2 by reducing miR-4465 levels in ovarian cancer cells, which suggests that the pseudogenes may regulate gene expression through microRNAs." (PMID 37165454, 2023). "Depletion of lncRNA SDHAP1 stimulated paclitaxel sensitivity in ovarian cancer cells." (PMID 36105363, 2022). "Unexpectedly, SDHAP1 is classified as a lncRNA in ovarian cancer." (PMID 33153035, 2020). "Mechanically, lncRNA SDHAP1 sponged miR-4465 and promoted the expression of EIF4G2, which conferred paclitaxel-induced cell apoptotic death in ovarian cancer cells." (PMID 36105363, 2022). "The anticancer effect of SDHAP1 was accordant with that SDHAP1 upregulated EIF4G2 level by sponging miR-4465 and therefore promoted the PTX-induced apoptosis in ovarian cancer." (PMID 36438489, 2022). "In mechanism, SDHAP1 upregulates EIF4G2 expression through sponge miR-4465, thereby promoting PTX induced apoptosis in ovarian cancer cells." (PMID 34796116, 2021). "Studies have been shown that SDHAP1 was upregulated in PTX-resistant SKOV3 and Hey-8 ovarian cancer cell lines, while miR-4465 levels were down-regulated." (PMID 34796116, 2021). "Mechanistically, SDHAP1 was shown to increase the expression of the protein eukaryotic translation initiation factor 4 gamma 2 (EIF4G2) by acting as a decoy for miR-4465, which in turn promoted paclitaxel-induced cell death in ovarian cancer cells." (PMID 41362671, 2026). "The regulatory network involving the interactions between SDHAP1, miR-4465, and EIF4G2 could represent a promising therapeutic target for treating ovarian cancer that has developed resistance to paclitaxel chemotherapy." (PMID 41362671, 2026). "The regulatory networks involving SDHAP1, miR-4465 and EIF4G2 participate may be potential therapeutic targets for PTX-resistant ovarian cancer." (PMID 34796116, 2021).
tumor (3 papers, 2020 to 2025). "In OC, HMGA1P6, CTSLP8, and SDHAP1 are known to competitively bind to their paralogs, influencing tumour metastasis and paclitaxel resistance." (PMID 40000433, 2025). "The composite plot indicated that SDHAP1, SDHAP3, DDX12P, CLUHP3, and RRN3P3 demonstrated high expressions in the low-risk subtype, which were categorized as tumor-suppressor pseudogenes in our study." (PMID 36438489, 2022). "Compared to HPV negative, patients with HPV positive had significantly higher expressions of oncogene pseudogenes (SDHAP1, SDHAP3, DDX12P, CLUHP3, and RRN3P3), but there was no prominent difference in the expressions of tumor-suppressor pseudogenes (PDIA3P1, LDHAP4, LDHAP7, EEF1A1P6, and EEF1A1P11)." (PMID 36438489, 2022).
cancer (1 paper, 2023). A tumor composed of atypical neoplastic, often pleomorphic cells that invade other tissues. "SDHAP1, ZDHHC8P1, and DIO3OS were significantly differentially expressed in several cancer types." (PMID 36221911, 2023).
SDHAP1 also shares sentences with these, for which no sentence is quoted: breast carcinoma (1 paper); colon cancer (1); pancreatic cancer (1); squamous cell lung carcinoma (1).